IL13 (interleukin 13)
Diseases named in the same sentence as IL13 in open-access papers (continued):
Sharing a sentence is not in itself a finding about the gene and the disease.
melanoma (42 papers, 2009 to 2025). A malignant, usually aggressive tumor composed of atypical, neoplastic melanocytes. "Recent studies by the Strober group also highlighted the importance of IL-13Rα2 in the progression of malignant melanoma, where its activation by IL-13 caused TGF-β1 elaboration, which inhibited tumor immune surveillance and favored tumor growth." (PMID 23972995, 2013). "For example, IL-13-functionalized long-circulating liposomes (IL-13-LCL-SIM) and PEGylated extracellular vesicles (PEG-EV-DOX) were designed to disrupt crosstalk between tumor-associated macrophages (TAMs) and melanoma cells." (PMID 40861441, 2025). "Here, we expanded the discoveries concerning the cytokines in melanoma based on some relevant results in our current study, where it was evident that the levels of IL-4, IL-13 and IL-35 in melanoma were all elevated following the silencing of EBI3." (PMID 39726752, 2024). "The relevant results have demonstrated that the concentrations of these specific cytokines including IL-35, IL-4 and IL-13 were all higher in melanoma cells with the presence of EBI3-specific small interfering RNA (p-value < 0.05)." (PMID 39726752, 2024). "On the other hand, IL-13 can recruit and activate neutrophils and macrophages within the tumor lesion, with cytotoxic activity against melanoma cells." (PMID 35173725, 2022). "Accordingly, IL-13-LCL-SIM treatment on M2 macrophages prior to being co-cultured with melanoma cells slightly decreased their pro-proliferative functions, more efficiently than LCL-SIM." (PMID 35450036, 2022). "Their latest study proposed a combination therapy with simvastatin incorporated in IL-13-functionalized long-circulating liposomes (IL-13-LCL-SIM) based on PEG-EV-Dox to selectively target both tumor-associated macrophages and melanoma cells." (PMID 36466338, 2022). "CD40 expression on melanoma cells stimulates the formation of CD8 T cell cytokines including IL-13, IL-6, TNF-α, and granulocyte/macrophage colony-stimulating factor (GM-CSF) and impedes brain metastasis which is common among melanoma patients." (PMID 32902664, 2021). "In response to autologous melanoma cell line, this clone is lytic and produced in decreasing order the following Th1 and Th2 cytokines: IL-13, IL-4, TNF-α, GM-CSF, IL-2, IFN-γ and IL-5." (PMID 20052413, 2010). "In addition to modulating transcriptional programs, mitochondrial ROS facilitate the release of inflammatory cytokines, such as transforming growth factor beta (TGF-β) and interleukin 13 (IL-13), from melanoma cells." (PMID 40721981, 2025). "Melanoma exosomes have been shown to induce a spectrum of macrophage phenotypes secreting a variety of anti-inflammatory (IL-4, IL-10, IL-11, and IL-13) but also pro-inflammatory (TNF-α, IL-12B, IL-1β, IL-6, iNOS, and CCL22) factors, reflecting the spectrum of phenotypes detected in the TME." (PMID 38533720, 2024). "Cytokines such as IL-4, IL-13, TGFβ, and IL-10 were most probably present in the melanoma-microglia interface and could have provided a variety of signals that led to divergent M1/M2 phenotypes." (PMID 37296634, 2023). "Our data revealed that 5 mg/kg SIM encapsulated in IL-13-LCL-SIM elicited the strongest inhibitory effect on B16.F10 melanoma growth compared to the effects of the same concentration of SIM encapsulated in LCL-SIM (by 55% inhibition, p < 0.05) and to free SIM (by 68% inhibition, p < 0.01)." (PMID 35450036, 2022). "Both TNFα and IL-13 have been suggested to exert a positive role against melanoma cells." (PMID 35173725, 2022). "In accordance with our in vitro data showing that IL-13-conjugated liposomes are preferentially taken up by M2 macrophages, IL-13-LCL-SIM monotherapy generated a strong reduction of intratumor macrophage marker F4/80 in the melanoma microenvironment (p < 0.001)." (PMID 35450036, 2022).
melanoma (continued). "At functional level, we showed an impaired secretion of TNFα by both CD117- ILCs and CD117+ ILCs from melanoma patients, as reported in blood tumors, and the capability of Nivolumab to enhance the secretion of IL-13 and TNFα by ILC2s and CD117+ ILCs, respectively." (PMID 35173725, 2022). "In contrast, the monomeric IL-13Rα2 receptor is mostly absent in normal tissues, it is overexpressed in melanoma and other solid tumors, and it constitutes a “private chain” for high-affinity binding and sequestration of IL-13, serving as a potential target for counteracting melanoma progression." (PMID 35450036, 2022). "The vaccine (IDD-3) consisted 8 doses of autologous monocyte-derived matured DC generated in serum-free medium with granulocyte macrophage colony stimulating factor (GM-CSF) and interleukin-13 (IL-13), pulsed with lysates of three allogeneic melanoma cell lines, and matured with interferon gamma." (PMID 20875102, 2010). "In addition, it has been documented that IL-13 and IL-4 downregulated arginase production in melanomas, leading to down-regulation of CD3ζ expression thus limiting T cell function." (PMID 20052413, 2010). "We also found evidence that regulating NKT cells could be involved in the immune response against B16F10-Nex2 melanoma in the mouse by the protective effect exerted by the neutralization of IL-13 using an IL-13Rα2-Fc chimera, enhanced by IL-12." (PMID 19968878, 2009). "Additionally, IL-4 and IL-13 from group 2 innate lymphoid cells suppressed antitumor immunity in a colorectal cancer model, and the production of IL-13 by group 2 innate lymphoid cells was upregulated by melanoma cells in vitro." (PMID 39598436, 2024). "Findings showed that sequential intravenous administration of IL-13-LCL-SIM and PEG-EXO-Dox had the most powerful antiproliferative outcome on melanoma cells." (PMID 40356952, 2025). "Our data showed that the IL-4 polarized M2 macrophages, which express a phenotype similar to the “M2-like” phenotype of TAMs, were the most efficient in taking up the IL-13-LCL in vitro, compared to M1 (antitumoral) macrophages and to B16.F10 melanoma cells." (PMID 35450036, 2022). "By combining the novel IL-13-LCL-SIM formulation with PEG-EV-DOX, we aimed to target both the protumoral M2-like phenotype of TAMs and the developmental capacities of melanoma cells." (PMID 35450036, 2022). "The results demonstrated that sequential administration of IL-13-LCL-SIM and PEG-EV-Dox had the most potent antiproliferative effect on melanoma cells." (PMID 36466338, 2022). "A similar trend was observed after 30 min incubation, IL-13-LCL being preferentially uptaken by M2-polarized macrophages compared to M1-polarized macrophages (p < 0.05) and B16.F10 melanoma cells (p < 0.01)." (PMID 35450036, 2022). "In the interleukin-4 and interleukin-13 signaling pathway, CXCL8 and MMP3 have published roles in melanoma growth and metastasis." (PMID 35008167, 2021). "The A375-A2-ESO human melanoma cells, ESO-T cells, and IL-4/IL-13-polarized MDMs were mixed at a 2:2:1 ratio and placed in a 3D tumor organoid culture mimicking TME." (PMID 34112755, 2021). "Melanoma-derived soluble factors and metabolites, such as TGF-β, IL-10, IL-4, and IL-13 May contribute to this shift toward acquisition of pro-tumorigenic features." (PMID 38533720, 2024). "Melanoma cells addition up-regulated TNFα in all the three ILC subsets and IL-13 in ILC2s." (PMID 35173725, 2022). "Notably, IL-13-LCL-SIM and PEG-EV-DOX administered sequentially inhibited almost totally the growth of B16.F10 melanoma tumors, at day 12, when mice were euthanized." (PMID 35450036, 2022). "Moreover, melanoma cells boosted TNFα production in all ILC subsets and increased the number of IL-13 producing ILC2s in vitro." (PMID 35173725, 2022).
melanoma (continued). "We also assessed expression of activation-responsive immune genes TNF, IL21, IL10, IL13, and CFS2 in the ICB melanoma dataset, and found that IFNG, TNF, and interleukins IL21 and IL10 seemed to increase upon treatment in responders, even though they were not differentially expressed." (PMID 32471032, 2020). "IL-13 did not affect the proliferation of the SK-MEL-28 or A375 melanoma cells in the present study; however, previous study in a colorectal cancer epithelial cell line HT-29 revealed that IL-13 signal interfered with cell proliferation by inducing cell death." (PMID 30718742, 2019). "IL-13-PE has also been shown to work synergistically with paclitaxel in an immunodeficient animal model of HNSCC with gemcitabine for pancreatic cancer and a DNA vaccine of IL-13Rα2 in melanoma, breast, and sarcoma tumor models." (PMID 23421960, 2013). "In this context, the current study explored the efficacy of a novel targeted therapy consisting of the sequential administration of IL-13-functionalized long-circulating liposomes encapsulating SIM and EVs stabilized with PEG and loaded with doxorubicin (DOX) on B16 melanoma." (PMID 35450036, 2022). "There are several other cytokines such as IL-4 and IL-13 that are known to have a negative impact on survival and which would have been interesting to examine here, especially as we previously found that IL 4 was relevant in melanoma." (PMID 26500775, 2015). "Though Nivolumab did not significantly alter serum cytokine profiles, in melanoma patients we observed a deviation from the physiological range for 7 out 18 cytokines tested: IL-1β, IL-6, CCL2, CXCL8, VEGF, IL-5 and IL-13." (PMID 35173725, 2022). "Finally, although this study observed changes in IL-35, IL-4, and IL-13 levels after knockdown of EBI3, the specific role of these cytokines in melanoma was not analyzed in detail." (PMID 39726752, 2024). "In Braf/Pten melanoma-draining LNs, TSLP promoted not only GATA3+ Th2 cells, but also GATA3+ Tregs expressing a specific signature including ST2, CCR8, ICOS, PD-1, CTLA-4, OX40, and IL-10 — but not Th2 cytokines IL-4 and IL-13." (PMID 36107619, 2022).
Sepsis (42 papers, 2007 to 2025). Sepsis is defined as life-threatening organ dysfunction caused by a dysregulated host response to infection. "By contrast, both IL‐13+ cells in ILC2s and IL‐13+ ILC2s in total leukocytes of skeletal muscle in sepsis were significantly augmented with PD‐1 deficiency." (PMID 39016179, 2024). "Studies have reported that IL13 is associated with mitochondrial dysfunction in patients with sialadenitis and protects the mitochondria of cardiomyocytes in patients with septicemia." (PMID 36497047, 2022). "In summary, our investigations have demonstrated the importance of IL-13 in alleviating myocardial apoptosis caused by sepsis." (PMID 34616745, 2021). "In contrast, the Th type 2 (Th2) responses (secrete IL-4, IL-5, IL-13 and IL-10) were elevated, leading to a suppressed adaptive immune response and increased susceptibility to sepsis." (PMID 34209240, 2021). "Anti-inflammatory IL-10 cytokine signaling pathway was over-represented, which is a well characterized mediator of immunosuppression in severe sepsis, and IL-4/IL-13 pathways associated with M2 (and reprogrammed) macrophages that have been associated with sepsis." (PMID 37304268, 2023). "All these results suggest that IL-13 has therapeutic potential in cardiomyopathy caused by sepsis." (PMID 34616745, 2021). "Previous study reported that IL13 is an anti-inflammatory cytokine that reduces inflammatory cytokine production in sepsis." (PMID 39886603, 2025). "IL‐13 has been shown to prevent diaphragm muscle weakness in an LPS‐induced sepsis model, supporting the in vivo protective effects of this cytokine." (PMID 39016179, 2024). "The sensitivity of skeletal muscles to IL‐13 was thought to be the most noticeable in the PD‐1 KO sepsis mice." (PMID 39016179, 2024). "ILC2‐derived IL‐13 production in skeletal muscles was increased in PD‐1 KO mice, thereby suggesting that IL‐13 alleviates muscle weakness during sepsis." (PMID 39016179, 2024). "PD‐1 KO mice capable of better producing ILC2‐derived IL‐13 preserved the muscle strength in sepsis." (PMID 39016179, 2024). "To ask if IL‐13 has any capacity to modify slow‐twitch‐specific gene expression in sepsis, we next employed an in vitro model of sepsis‐induced skeletal muscle pathology." (PMID 39016179, 2024). "Combined with the previous reports highlighting the importance of IL‐13 in sepsis, IL‐13 is considered to be decreases in sepsis‐induced muscle weakness." (PMID 39016179, 2024). "Collectively, the PD‐1/ILC2/IL‐13 axis is supposed to be involved in the the pathogenesis of ICU‐AW by sepsis." (PMID 39016179, 2024). "We found that the frequency of IL‐13+ cells in ILC2s was higher than that in T cells of skeletal muscle of WT mice in both sham and sepsis conditions, using flow cytometry analysis." (PMID 39016179, 2024). "Our finding indicating that IL‐13 restores the sepsis‐induced decrease in expression of Mb, Tnni1, and Myh7 at the transcriptional level would support the potential roles of IL‐13 in improving or preserving muscle atrophy and weakness in sepsis." (PMID 39016179, 2024). "Our present study provides new insight into PD‐1/ILC2/IL‐13 axis‐ involved anabolic dysregulation in sepsis in aspects of the perspective of immune metabolism." (PMID 39016179, 2024). "In a murine sepsis model, IL-13 protected mice from lethality, and an IL-13 blockade decreased survival from peritonitis." (PMID 37629063, 2023). "For the anti-inflammatory cytokines (IL-4, IL-5, IL-10, IL-13), only the concentrations of IL-1RA showed a significant difference between children with sepsis compared to children with either clinical malaria or febrile controls." (PMID 35811678, 2022). "Some studies reported that IL-13 level was increased after sepsis, while other studies argued that IL-13 was decreased after sepsis." (PMID 34616745, 2021). "In a previous study, IL-13 protected against sepsis-induced lethality by suppressing inflammatory responses." (PMID 34499695, 2021).
Sepsis (continued). "We found that the serum markers of myocardial injury were noted to return to the normal level 12 h after sepsis, when IL-13 transcription was further enhanced but protein expression was decreased." (PMID 34616745, 2021). "In the regulation of cytokine production, some cytokines had been proved to be beneficial for the control of sepsis, such as the anti-inflammatory cytokines of IL-1Ra, IL-4, IL-6, IL-10, IL-11, IL-13, IL-35, and TGF-β." (PMID 34938184, 2021). "In the present study, we used LPS-treated mice or primary cardiomyocytes as a sepsis model to explore the anti-apoptotic ability of IL-13." (PMID 34616745, 2021). "It was found that an increased level of exogenous IL-13 was beneficial to the recovery of heart function in sepsis, and this anti-apoptotic effect of IL-13 was probably through enhancing the phosphorylation of STAT3 Ser727." (PMID 34616745, 2021). "The results of this study showed that IL-13 protected cardiomyocytes against apoptosis during sepsis." (PMID 34616745, 2021). "Cats with sepsis showed significantly higher concentrations of IL-13, MCP-1, and IL-18 compared to cats with septic shock and healthy controls." (PMID 32548135, 2020). "In our study, sepsis simultaneously induced low levels of IL-13 production and high levels of PD-1 expression on ILC2s during the early phase of sepsis (CLP day 1)." (PMID 33053762, 2020). "Although IL-33/ST2 signaling in ILC2s was robust, IL-13 secretion remained low during the early phase of sepsis." (PMID 33053762, 2020). "Blocking IL-13 in a CLP-induced sepsis mouse model revealed worse rates of mortality and lung injury, which are associated with increased neutrophil-activating chemokine and proinflammatory cytokine levels in the lungs." (PMID 33053762, 2020). "In short, IL-13 production by ILC2s in the lung was initially inhibited by sepsis, but then gradually increased." (PMID 33053762, 2020). "We then measured plasma concentrations of IL-9 and IL-13 following sepsis, and demonstrated that both cytokines were markedly increased between 12 and 24 h after CLP." (PMID 29511181, 2018). "To characterize the type 2 cytokines secreted from lung ILC2 following sepsis, we measured IL-4, IL-9, and IL-13 expression in the ILC2 increased in the lungs by flow cytometry." (PMID 29511181, 2018). "Collectively, these data indicate that IL-33/ST2 and IL-4/IL-13/STAT6 signalling are required for the expansion of Treg cells in sepsis-surviving mice, linking IL-10-secreting M2 macrophage in this process." (PMID 28374774, 2017). "Correspondingly, we found a significantly lower number of IL-13-producing ILC2s in the lung of sepsis-surviving Il1rl1−/− mice on day 7 after CLP compared to sepsis-surviving WT mice." (PMID 28374774, 2017). "IL13 blockade in experimental sepsis has been shown to decrease survival and increase the expression of inflammatory cytokines." (PMID 26064774, 2015). "Recent studies have documented elevated levels of IL-1 beta, IL-6, IL-7, IL-8, IL-10, IL-13, and tumour necrosis factor-alpha in septic shock patients than in those with severe sepsis." (PMID 20490277, 2010). "This study demonstrates the effects of PD‐1 blockade in preserving muscle strength during sepsis through an increase in ILC2‐derived IL‐13 and may be an attractive therapeutic target for sepsis‐induced ICU‐AW." (PMID 39016179, 2024). "Our current study proposes that ILC‐derived IL‐13, which can be increased by a PD‐1 blockade, may contribute to improving any sepsis‐inhibited anabolism, and consequently ameliorating ICU‐AW." (PMID 39016179, 2024). "We next measured the ratio of IL‐13+ cells in intramuscular ILC2s of WT and PD‐1 KO mice in sepsis." (PMID 39016179, 2024). "In addition, PD‐1 KO mice showed a significantly increased level of ILC2‐produced IL‐13 and a treatment of IL‐13 to the myotubes enhanced their expressions of slow‐twitch genes in the condition mimicking sepsis." (PMID 39016179, 2024).